PKD1 (polycystin 1, transient receptor potential channel interacting)
Diseases named in the same sentence as PKD1 in open-access papers (continued):
Sharing a sentence is not in itself a finding about the gene and the disease.
cardiac hypertrophy (18 papers, 2012 to 2026). "Lastly, protein kinase D (PKD) has also been implicated in cardiac hypertrophy, in which PKD1 was shown to phosphorylate class II histone deacetylases, which led to HDAC translocation out of the nucleus and induction of pro-hypertrophic genes." (PMID 33668293, 2021). "PKD1 is not only a contraction-activated kinase, but also for a longer time known to be involved in cardiac hypertrophy." (PMID 41596248, 2026). "Protein kinase D1 (PKD1) is a key player in the development of cardiac hypertrophy and has been studied as a potential target to restore cardiac function in the hypertrophied heart." (PMID 41596248, 2026). "A recent study identified a complex formed between the catalytic domain of PKD1 and Hsp20, which is essential for PKD1 nuclear translocation and downstream signaling events leading to cardiac hypertrophy." (PMID 33807058, 2021). "On the other hand, several studies have reported a role for the PKD1-pathway in relation to cardiac hypertrophy." (PMID 33807195, 2021). "The Olson group reported that cardiac-specific deletion of PKD1 diminished cardiac hypertrophy and improved cardiac function in response to pressure overload, chronic adrenergic stimuli, or angiotensin II signaling in mice." (PMID 33807058, 2021). "In a separate study using a transverse aortic constriction-induced cardiac hypertrophy mouse model, the authors found that PKD1 contributed to cardiac hypertrophy through inhibiting AKT/mTOR regulated cardiac autophagy." (PMID 33807058, 2021). "Cardiac-specific PKD1-cKO mice show resistance to cardiac hypertrophy and fibrosis in response to pressure overload and angiotensin II treatment." (PMID 32351396, 2020). "A number of compounds, such as α-adrenergic agonists, are known to induce PKD1 activation, but also to induce a variety of other signaling pathways with rather undesirable side actions such as cardiac hypertrophy." (PMID 32102213, 2020). "This notion is boosted by the observation that PKD1 overexpression in the heart is sufficient by itself for the development of a severe form of cardiac hypertrophy." (PMID 29930945, 2018). "With respect to the cardiovascular system, PKD1 has been studied mainly in the context of cardiac hypertrophy and remodeling." (PMID 29930945, 2018). "Powerful genetic evidence for a crucial role of PKD1 in cardiac hypertrophy comes from studies with mice with cardio-specific overexpression of a constitutively active PKD1 mutant." (PMID 29930945, 2018). "This suggests a possible role for the PKD1-pathway in the development of cardiac hypertrophy." (PMID 33807195, 2021). "Also remarkably, PKD3, just like PKD1, is involved in mediating the morphological and functional changes as seen during the development of cardiac hypertrophy." (PMID 29930945, 2018). "Interestingly, PKD1's closely related relatives PKD2 and PKD3 have also been implicated in the regulation of cardiac glucose uptake and cardiac hypertrophy, together resulting in a complex signaling network." (PMID 29930945, 2018). "On top of this, PKD1 activation decreases CD36 expression in a FOXO1-dependent manner (see section “PKD1 and Regulation of Lipid Uptake”), which further may contribute to the development of cardiac hypertrophy." (PMID 29930945, 2018). "For example, as protein kinase D1 (PKD-1) activator, LPA promotes angiogenesis and microvascular remodeling, which are closely associated with cardiac hypertrophy." (PMID 30283359, 2018). "Dysregulation of PKD1 leads to the development of cancer and cardiac hypertrophy." (PMID 27266874, 2016). "Furthermore, our previous work revealed that AKAP-Lbc promotes cardiac hypertrophy through activation of a protein kinase D1 (PKD1)-mediated signaling pathway." (PMID 25802336, 2015). "Furthermore, PKD1 has been proposed to facilitate cardiac hypertrophy through the phosphorylation of HDAC5 (histone deacetylase isoform 5) at Ser259 and Ser498." (PMID 24219103, 2014).
cardiac hypertrophy (continued). "Moreover, these beneficial effects of MI14 can be extended to other cardiomyocyte models of hypertrophy than PE stimulation, as MI14 also successfully inhibited the maladaptive increases in glucose uptake in cardiomyocytes with PKD1 overexpression, another model of cardiac hypertrophy." (PMID 41596248, 2026). "Thus, it would be interesting to know whether LPA-mediated vascular remodeling and PKD-1 signaling is responsible for cardiac hypertrophy." (PMID 30283359, 2018). "However, over-activation of cardiac PKD1 in absence of high-fat diet causes cardiac hypertrophy through a mechanism involving phosphorylation of histone deacetylase-5 (HDAC5) and subsequent release of the transcription factor MEF2 to initiate hypertrophic programming." (PMID 33090289, 2021). "Recently, another mechanism via which PKD1 may contribute to cardiac hypertrophy, has been revealed by using the transverse aortic constriction (TAC)-induced cardiac hypertrophy mouse model." (PMID 29930945, 2018). "In addition to demonstrating that AKAP-Lbc mobilizes a prohypertrophic signaling pathway through PKD1, we also demonstrated the importance of AKAP-Lbc-tethered PKA in the induction of cardiac hypertrophy through knockdown/rescue experiments." (PMID 25802336, 2015). "Given that PKD1 is positioned at the crossroad between stimulation of cardiac glucose uptake and hypertrophic signaling and that hypertrophy can be beneficial short-term, we sought to look downstream of PKD1 and to directly target cardiac metabolism rather than cardiac hypertrophy." (PMID 41596248, 2026). "Although PKD1 is by far the most abundant isoform in the heart, PKD3 has also been reported to mediate glucose uptake and account for the morphological and functional changes as seen during the development of cardiac hypertrophy driven by cardiac transcription factors." (PMID 33807058, 2021). "The activation of MEF2 is not the only action of PKD1 involved in cardiac hypertrophy." (PMID 29930945, 2018). "Activated PKD1 then phosphorylates class II histone deacetylases to promote their nuclear export, leading to the derepression of the transcription factor MEF2, resulting in cardiac hypertrophy and tissue remodeling through MEF2-dependent transcription of hypertrophic genes." (PMID 25802336, 2015). "A plausible interpretation of such data is that PKD1 regulates cardiac hypertrophy through a mechanism that is independent of its kinase activity, in which case FHL1- and FHL2-mediated regulation of neurohormonal PKD activation would be more likely to regulate other PKD-mediated functions." (PMID 24219103, 2014).
gastric cancer (12 papers, 2009 to 2023). A primary or metastatic malignant neoplasm involving the stomach. "In a panel of gastric cancer cell lines, the loss of PKD1 mRNA was detected in over 70% of all the cell lines assessed." (PMID 26848698, 2016). "Moreover, loss of PKD1 has been associated with increased invasiveness and risk of metastases in gastric cancer and osteosarcoma." (PMID 23971832, 2013). "Primary gastric tumors and gastric cancer cell lines also have low levels of PKD1, and PKD1 is downregulated in androgen-independent prostate cancers, as well as in non-small cell lung cancer (NSCLC)." (PMID 37293129, 2023). "In particular, studies conducted in prostate, breast and gastric cancer cells have showed that altered PKD1 expression or activity suppressed tumor cell motility." (PMID 30419840, 2018). "In gastric cancer, PKD1 expression is decreased in gastric tumors and cell lines due to PKD1 promoter hypermethylation, and knockdown of PKD1 increased the invasiveness of gastric tumor cell lines." (PMID 30419840, 2018). "Similar functions for PKD1 on tumor cell invasion were described for other cancers including prostate and gastric cancer." (PMID 22276203, 2012). "PKD1 has been reported to be downregulated in advanced prostate, breast and gastric cancers and shown to play a role in tumorigenesis and metastasis." (PMID 22511927, 2012). "In 59% gastric cancer samples examined, PKD1 has a >2-fold decrease in expression due to epigenetic silencing." (PMID 22511927, 2012). "PKD1 expression is downregulated in androgen-independent prostate cancer and the PKD1 promoter is epigenetically-silenced by methylation events in gastric cancer." (PMID 19243594, 2009). "A similar downregulation of PKD1 was also recently described for other cancers such as prostate and gastric cancer." (PMID 19243594, 2009). "In gastric cancer it was recently shown that PKD1 is downregulated in its expression by DNA methyltransferases." (PMID 19243594, 2009). "Similarly, aberrant methylation of the PKD1 gene promoter influenced migration and metastasis in gastric cancer." (PMID 36768307, 2023). "For example, PKD1 plays a crucial role in gastric cancer cell migration and invasion." (PMID 36192427, 2022). "In contrast, PKD1 functions as a tumor suppressor in invasive breast and gastric cancers." (PMID 34858418, 2021). "Depletion of PKD1 in gastric cancer cells augmented their invasion capability." (PMID 26848698, 2016). "Moreover, in breast, prostate and gastric cancer cell lines PKD1 expression and activity reversely correlate with the migratory potential and invasiveness." (PMID 22276203, 2012). "The inactivation of PKD1 expression via PRKD1 methylation was also found in primary gastric tumors and gastric cancer cell lines, and significantly correlated with age." (PMID 37293129, 2023). "In a recent report in gastric cancer where low PKD1 and high PKD2 expression were detected in poorly differentiated adenocarcinoma, overexpression of PKD1 had no/minimal effects on tumor cell survival and proliferation, which is consistent with our findings." (PMID 30419840, 2018).
autosomal recessive polycystic kidney disease (11 papers, 2015 to 2025). "The COL27A1 variant is suggested to be responsible for the skeletal phenotypic features, whereas the homozygous variant in PKD1 is considered to be a hypomorphic dominant allele causing features of autosomal recessive polycystic kidney disease." (PMID 34974531, 2022). "The study also identified pathogenic mutations in PKD1 and PKHD1, responsible for autosomal dominant and autosomal recessive polycystic kidney disease, respectively, demonstrating the utility of NGS in resolving genetically complex regions and improving diagnostic yield." (PMID 41288877, 2025). "Mutations in PKD1 and PKHD1 were identified in separate patients, representing autosomal dominant and autosomal recessive polycystic kidney disease (ADPKD and ARPKD), respectively." (PMID 41288877, 2025). "ECPKD was also enriched for PKHD1, which encodes fibrocystin, interacts with PKD1 and is associated with autosomal recessive polycystic kidney disease (PKD) (log2FC=0.96, adjusted P=1.1×10−56), although PKD1 was not within the list of DEGs." (PMID 40114603, 2025). "ADPKD is typically a late-onset disease and mainly caused by mutations in PKD1 or PKD2, but about 2–5% of patients show an early and severe phenotype that is clinically often indistinguishable from autosomal recessive polycystic kidney disease (ARPKD)." (PMID 25646624, 2015). "Renal cysts are genetically heterogeneous conditions and both PKD1 and PKD2 genes from dominant form, can be inherited in a recessive way, known as autosomal recessive polycystic kidney disease (ARPKD)." (PMID 36538546, 2022).
nephronophthisis (11 papers, 2019 to 2024). Progressive tubulointerstitial injury, inherited in an autosomal recessive pattern, caused by mutations in genes involved in ciliary function, which may result in an end stage renal failure. "In the other 10 patients, the sequencing of PKD1 and panel of genes yielded the diagnosis in additional 5 of them (nephronophthisis in 4 patients, 1 patient with ADPKD-VEO)." (PMID 32574212, 2020). "The significance of synonymous variants in PKD1 and NPHP3, underlying ADPKD and nephronophthisis, respectively, has recently been described." (PMID 33059616, 2020).
renal fibrosis (11 papers, 2016 to 2024). A final common manifestation of a wide variety of chronic kidney diseases characterized by glomerulosclerosis and tubulointerstitial fibrosis. "In ADPKD, mutation of PKD1 is often associated with renal fibrosis, which contributes to scarring and loss of kidney function." (PMID 37542051, 2023). "Our findings showed that chronic exposure to smoking had a deleterious effect on the renal phenotype of Pkd1-deficient cystic mice, accelerating cystic growth and renal fibrosis as well as reducing renal function." (PMID 34262092, 2021). "Another key feature of this study shows that targeting STING decreases renal fibrosis in Pkd1 mutant mouse kidneys through regulating the expression of fibrotic markers." (PMID 39456148, 2024). "The degree of renal fibrosis, as determined by the histomorphological analysis of Masson’s trichrome stain, significantly increased by five-fold in Pkd1 miR Tg mice compared with wild-type control mice (p < 0.05)." (PMID 30585217, 2018). "Knockout of MIF also decreases renal fibrosis in Pkd1 mutant mouse kidneys, and knockdown of CD74 blocks MIF induced the expression of fibrotic markers, supporting a novel mechanism that MIF is through CD74 to regulate the transcription of fibrotic markers followed by renal fibrosis." (PMID 38534333, 2024). "Furthermore, the mRNA expression of the renal fibrosis-related genes Col1a2, Fn1, and Tgfb1 were all significantly increased in Pkd1 miR Tg mice (p < 0.05) compared with wild-type mice." (PMID 30585217, 2018). "Unlike the preceding three ADPKD models, Cre/loxP recombination is not required to induce Pkd1 mutation, and these mice develop significant renal fibrosis." (PMID 28205547, 2017). "However, whether targeting MIF also decreases renal fibrosis in Pkd1 mutant kidneys remains unknown." (PMID 38534333, 2024). "Remarkably, the increase in renal fibrosis promoted by smoking was much higher in cystic than noncystic mice, revealing positive interaction between smoking and Pkd1 deficiency (P = 0.003) [0.09% (0.04–0.09) in NC, 0.13% (0.09–0.19) in NCS, 0.25% (0.20–0.66) in CY, and 1.20% (0.88–1.92) in CYS]." (PMID 34262092, 2021). "We also found that knockdown of p68 decreased the mRNA levels of fibronectin, α-SMA and collagen-1 in Pkd1-mutant PN24 cells and Pkd1 null MEK cells, which suggested that upregulation of p68 might promote renal fibrosis by upregulating fibrotic markers in ADPKD." (PMID 32724471, 2020).
Obesity (10 papers, 2016 to 2025). Accumulation of substantial excess body fat. "Clearly, PKD1 must be further investigated, especially its role in obesity-associated breast tumorigenesis." (PMID 27042159, 2016). "Through genome-wide association studies (GWAS), PKD1 was identified as a loci associated with human obesity, especially in obesity prevalent young adults, which is similar to the window of diet exposure and latency in this study." (PMID 27042159, 2016). "For example, adipocyte-specific knockout of PKD1 improved insulin and glucose tolerance in vivo, conferred protection against obesity and T2D, and promoted the formation of beige adipocytes." (PMID 41349796, 2025). "GWAS studies show that PRKD gene is associated with body mass index, suggesting the involvement of PKD-1 signaling in the pathobiology of diet-induced obesity." (PMID 27200349, 2016). "Of great relevance to studies presented herein, PKD1 is one of the few genes identified as regulator of obesity in human populations." (PMID 27042159, 2016). "Our study implicates that diet-induced obesity may promote tumor progression via LPA/PKD-1 signaling-mediated angiogenesis." (PMID 27200349, 2016). "Further understanding molecular aspects of PKD-1 signaling in the regulation of angiogenesis may have translational implications in obesity, cardiovascular disease, and cancer." (PMID 27200349, 2016). "To test the hypothesis that LPA signaling promotes the expansion of BCSCs via PKD-1, we examined the expression of PKD-1 in a syngeneic BC model in mice with high-fat diet (HFD)-induced obesity that generates excessive LPA22 and in mice on a normal diet with or without the administration of LPA." (PMID 34168243, 2021). "In light of the potential modulatory role for PKD1 phosphorylation on serine 916, it is therefore intriguing to speculate that the FFA receptor GPR40 and autocrine P2Y1 signaling may exert synergistic effects via PKD1 when FFAs are elevated in high‐fat diet or human obesity." (PMID 31591827, 2019).
tuberous sclerosis complex (10 papers, 2016 to 2025). "Mutations in the TSC2 gene and mutations in the adjacent PKD1 gene lead to the overlapping syndrome of tuberous sclerosis and polycystic kidney disease." (PMID 39201746, 2024). "The deletion region comprises TSC2, PKD1, TBC1D24 and ABCA3 genes and mutations of these genes are associated with tuberous sclerosis complex, autosomal dominant polycystic kidney disease type 1 (ADPKD1) or familial infantile myoclonic epilepsy." (PMID 31060568, 2019).